TNF (tumor necrosis factor)
Diseases named in the same sentence as TNF in open-access papers (continued):
Sharing a sentence is not in itself a finding about the gene and the disease.
tumor (continued). "Furthermore, mLama4-specific CD8+ TILs from T3-HDVax-treated mice expressed high levels of exhaustion markers (PD1, CD39, TIM3, LAG3 and TOX) and produced low amounts of IFNγ and TNF compared with similar populations from T3-LDVax-treated tumour-bearing mice." (PMID 39048822, 2024). "In obesity, AT produces elevated levels of estrogen, pro-inflammatory cytokines (TNFα, IL-6, IL-1β), adipokines (leptin), and EVs, which may contribute to enhanced tumor invasiveness, proliferation, and metastasis." (PMID 39697630, 2024). "Proinflammatory cytokines IL-1, IL-6, TNFα, and IL-17 play an important role in the regulation of inflammation and are capable of stimulating proliferative and antiapoptotic signals in epithelial and tumor cells or inducing angiogenesis." (PMID 39637122, 2024). "Reduced the levels of IL-1β, IL-6 and tumour TNF-α in cerebral tissue." (PMID 38585461, 2024). "Additionally, T cells activated by TCEs secrete a wide range of cytokines, including IL-2, IFN-γ (interferon γ) and TNF-α (tumor necrosis factor α), which enhance their anti-tumor effector function." (PMID 38672662, 2024). "Fusobacterium nucleatum can activate the nuclear factor-kappa B (NF-κB) pathway to stimulate the production and release of inflammatory cytokines, such as IL-1β, IL-6, IL-8, and tumor necrosis factor (TNF), thereby creating a proinflammatory microenvironment that favors tumor development." (PMID 38338956, 2024). "In addition, the levels of TNF-α in both the plasma and tumor were dramatically reduced by nobiletin." (PMID 39834817, 2024). "In addition, tumor cell-induced platelet aggregation around the tumor can protect tumor cells from natural killer cells and TNF-α-mediated cytotoxicity." (PMID 38915379, 2024). "In addition to immunosuppressive function, TAMs promote EMT and tumor stem cell differentiation in the Wnt/β-catenin pathway by secreting TNF-α." (PMID 39085965, 2024). "It is generally understood that PD-L1 expression can be induced in the tumor microenvironment under certain conditions, such as in the presence of inflammatory factors like interferons (IFNs), tumor necrosis factor-alpha (TNF-α), cell growth factors, hypoxic conditions, and exosomes." (PMID 38539470, 2024). "Moreover, various cytokines such as IL-1β and IL-6, known to promote tumor development and progression, are found in the tumor ECM, along with the immune activator TNF-α, which is linked to anti-tumor immune response." (PMID 38955827, 2024). "Increase the expression of NO, IL-1β, IL-6 and TNF-α in tumor-bearing mice." (PMID 39560523, 2024). "This enhancement is further characterized by increased production of interferon-gamma (IFN-γ) and interleukin-2 (IL-2) within the TME, concurrent with downregulation of tumor necrosis factor-alpha (TNF-α) and interleukin-10 (IL-10), thereby fortifying the host’s anti-tumor defenses." (PMID 38930435, 2024). "Additionally, TNF produced by OC cells enhances inflammation by stimulating production of cytokines, chemokines and angiogenic factors to promote tumor cell dissemination." (PMID 38566518, 2024). "However, upon BCG treatment, there was an induction of an inflammatory TME together with tumor clearance and apoptosis, which was highly dependent on TNF signaling." (PMID 39114912, 2024). "On the other hand, tumor cells secrete a variety of growth factors and cytokines, such as interleukin 6 (IL-6), tumor necrosis factor-α (TNF-α) and interferon-γ (IFN-γ), which may also lead to such results." (PMID 38180753, 2024). "Osteoclasts and tumor cells contribute to bone destruction, and neurotrophins, cytokines (IL-1β and TNFα), and other factors (ATP, TGFβ1, IGF-1, and sclerostin) play roles, suggesting potential intervention targets for improved pain management and enhanced patient quality of life." (PMID 38474093, 2024).
tumor (continued). "Paradoxically, a low dose paracrine TNF-α production in tumor areas may contribute to chronic inflammation and cancer progression." (PMID 39635522, 2024). "TNF-α from nearby tissues can activate the NF-κB pathway to support tumor growth." (PMID 38560169, 2024). "Upon activation, naïve CD8+ T cells proliferate and differentiate to generate effector CD8+ T cells, which, in turn, synthesize copious amounts of cytotoxic effector molecules (Granzyme B and Perforin) and inflammatory cytokines (IFN-γ and TNF-α) that kill tumor cells." (PMID 38755598, 2024). "ccRCC tumor cells secrete tumor necrosis factor (TNF), which acts as an autocrine growth factor." (PMID 38537932, 2024). "For instance, the anticancer efficacy of NK cells and subsequent tumor apoptosis could be enhanced by the interaction of tumor necrosis factor (TNF)-related apoptosis-inducing ligand receptors and Fas ligands." (PMID 38338836, 2024). "In addition, high levels of TNF-α and CD107a expression were found in tumor tissues of the treated group." (PMID 38261253, 2024). "In addition, the TNF-α/NF-κB/Snail signaling pathway has long been known to contribute to cancer development and metastasis through a tumor-nurturing pro-inflammatory microenvironment." (PMID 38714880, 2024). "Furthermore, silibinin inhibits signaling of nuclear factor kappa B (NF-κB), a key factor to mediate the expression of tumor-promoting cytokines, such as interleukin 6 (IL-6) and tumor necrosis factor α (TNF-α)." (PMID 38966629, 2024). "The activation of nuclear factor-κB (NF-κB) and associated signaling pathways and cytokines, such as TNFα, IL-6, and IL-1β, plays a key role in the development of CAC, which leads to imbalances in cell proliferation and differentiation and tumor transformation initiation." (PMID 39063041, 2024). "However, our study provides previously unexplored data showing the effect of different doses of TNF on receptor expression and changes in the proliferation, apoptosis, and transcriptome of tumor cell lines of various origins." (PMID 38651368, 2024). "Similarly, the role of TNF alpha inhibition in the progression of neoplastic diseases is a subject of questioning." (PMID 38610706, 2024). "Similarly, lingual denervation in vivo decreased TGFβ and PD-L1 expression and increased CD8+ T-cell infiltration and the expression of IFNγ and TNFα within tumor." (PMID 38324026, 2024). "Overall, positive associations between IL-6, IL-10, TNF-α, and inflammatory scores with all-cause mortality were evident among cases with non-triple-negative tumours but not among those with triple-negative tumours." (PMID 39342063, 2024). "TNF-α is a crucial component of the host defence system and kills tumour cells." (PMID 39739872, 2024). "TNF-α, a major cytokine in the tumour microenvironment, may promote the progression of tumours, while inhibiting the cytokine may cause a cessation of the antitumour immune response, thereby promoting the growth of immunogenic tumours." (PMID 39046819, 2024). "It has been suggested that modifications in the tumor microenvironment, such as increased levels of TNF-α, interferon-gamma, T cell infiltration, and reduced levels of interleukin-6 and interleukin-8, could be associated with irAEs and treatment outcomes." (PMID 39717410, 2024). "In CRC, TNF-α may contribute to establishing a protumorigenic inflammatory environment that facilitates tumor progression and resistance to anti-cancer therapies." (PMID 39727942, 2024). "Additionally, it enhances the expression of NKG2D, TNFα, and IFNγ in tumor tissues, hence promoting immune evasion by multiple myeloma cells." (PMID 39346921, 2024). "Functionally, M1 type macrophages activate the immune response mainly through the production of pro-inflammatory cytokines (e.g., tumour necrosis factor-α [TNFα], interleukin-1β [IL-1β], interleukin-6 [IL-6]) and inhibit tumour growth and spread by phagocytosis and killing of tumour cells." (PMID 39070147, 2024).
tumor (continued). "In addition, abnormal tumor TNF pathways mediated by abnormal expressions of TNF, NF-κB, FOS, JUN, and JUNB were observed, and scATAC-seq results confirmed the presence of abnormal accessibility binding sites for the transcription factors FOS, JUN, and JUNB." (PMID 38770048, 2024). "Furthermore, these nanoparticles stimulated CD4+ and CD8+ T cells and increased the secretion of IL-12 and TNF-α as anti-tumor cytokines." (PMID 38566199, 2024). "Consequently, the decreased expression of ZFP36L2 leads to the increased secretion of cytokines, such as IL1β, MMP-9, and TNF-α, by T cells, thereby promoting tumor apoptosis." (PMID 39767767, 2024). "Moreover, in TME, mast cell-derived PGD2 has limited the pro-tumor response by reducing TNF-α synthesis." (PMID 38704736, 2024). "Cytokines like IL6 and TNFα are secreted in the tumour microenvironment." (PMID 38339282, 2024). "Tumor necrosis factor α (TNF-α) is an inflammatory mediator in the tumor microenvironment." (PMID 39544302, 2024). "Considering that neutralizing low levels of cytokines such as TNF-α in the tumor microenvironment has positive results in cancer treatment, the use of nanobodies to control cytokines and also drug delivery in these environments has an attractive potential for clinical applications." (PMID 38341580, 2024). "Moreover, we observed heightened expression of IFN-γ and TNF-α effector cytokines in CD4+ T cells within the tumor-draining lymph nodes (dLN) of Flot2CD4 mice." (PMID 39499901, 2024). "For poorly differentiated CCA, intervention in tumor metabolism and inhibition of tumor growth may be attempted through targeting the TNF signaling pathway and modulating the AMPK signaling pathway." (PMID 39206584, 2024). "They secrete anti-angiogenic or immunostimulatory cytokines and chemokines to stimulate inflammatory responses, including TNF-α, interleukin (IL)-1β, IL-2, IL-6, IL-12, and IL-23, and may also act as tumor-suppressors." (PMID 39169402, 2024). "Studies have found that M2-TAM could regulate the T cell function, inhibit the NK cell activity and suppress the expressions of IFN-γ and TNF-α, thereby promoting immune escape of tumor cells." (PMID 38244580, 2024). "Because effector CD8+ T cells secreted IFNγ and TNF to regulate anti-tumor immunity and gene expression in tumor cells, we speculated that TNF and IFNγ secreted by activated CD8+ T cells may induce PRMT3 expression in HCC." (PMID 39256398, 2024). "However, osteoclastogenesis and osteoclast activity can be influenced by proinflammatory cytokines, such as tumor necrosis factor-α, which play important roles in inflammatory, infectious, and tumor processes." (PMID 39001355, 2024). "NK cells also release pro-inflammatory cytokines, such as IFN-γ and TNF, which can mediate anti-proliferative, anti-angiogenic and pro-apoptotic effects on tumour cells, as well as regulate the anti-tumour functions of other immune cells in the tumour-microenvironment (TME)." (PMID 39877370, 2024). "The killing effect of TNF-α requires prolonged contact between effector cells and target cells to further promote perforin protein activity, resulting in effective killing of most tumor cells." (PMID 38515134, 2024). "Terpenes like lupeol have been known to suppress tumour angiogenesis via downregulation of TNFα." (PMID 38400579, 2024). "The resulting tumor-associated antigens can also promote the infiltration of immune cells, such as CD3+ and CD8+ T cells, increasing the activation and release of related cytokines, such as TNF-α and IFN-γ." (PMID 38951911, 2024). "In addition to their direct effects on tumor cells, SKs regulate pathologic inflammation from cytokines such as TNFα and IL-6." (PMID 38730731, 2024). "IFN-γ and TNF-α regulate tumor development and progression in several cancers, including iCCA." (PMID 38672199, 2024).
tumor (continued). "In addition, the ELISA assay was used to measure the concentrations of IL-6 and TNF-α, which are critical in the regulation of the inflammatory response in the tumor microenvironment." (PMID 38926454, 2024). "In CRC, CSC-exo increases TNF-α expression in neutrophils, and this upregulation, stimulated by IL-1β, may lead to activation-induced cell death of T cells, thus intensifying tumor immune suppression." (PMID 39578849, 2024). "TNF-α is synthesized and secreted by monocytes and macrophages, which can promote the proliferation of B cells and enhance the immune response efficiency of T cells, thereby killing tumor cells or inhibiting their proliferation." (PMID 39109341, 2024). "In studies on tumors, resveratrol has been proven to downregulate the production of pro-inflammatory cytokines, such as TNF-α, IL-6, and IL-1β, and mitigating the inflammatory milieu within the tumor microenvironment hinders the development of angiogenesis, tissue invasion, and metastasis processes." (PMID 39458478, 2024). "Therefore, TGF-β and/or TNF-α within the tumor microenvironment trigger PAI-1 expression, controlling the immune surveillance escape mechanism by increasing PD-L1 expression." (PMID 38779680, 2024). "It is known that TNFα is involved in apoptotic events and in the regression of neoplasms." (PMID 38730981, 2024). "While both IL-10 as an anti-inflammatory cytokine control and a carrier control showed baseline spheroid growth, both IFN-γ and TNF could, individually, promote significant tumor spheroid growth." (PMID 38226976, 2024). "Additionally, mRNA levels of interleukin-6 and tumor necrosis factor-alpha and active forms of signal transducer and activator of transcription 3 and nuclear factor-kappa B p65 were significantly increased in the tumor tissues of VDUP1 KO mice." (PMID 39272794, 2024). "In some cases, TNF-α can promote tumor growth, while in others, it can induce tumor cell death." (PMID 38339276, 2024). "In HNSCC, TNF-α plays a key role in promoting angiogenesis, metastasis and tumor progression." (PMID 39726047, 2024). "Indeed, the presence of a tumor increases the expression of both Tumor Necrosis Factor (TNF) and Defensin." (PMID 39404408, 2024). "Additionally, they produce pro-inflammatory cytokines like IFN-γ and TNF-α, enhancing the immune response, and modulate the tumor microenvironment to promote anti-tumor immunity." (PMID 39468695, 2024). "Additionally, the expression levels of anti-tumor immune cytokines such as TNF-α, IL-12α, T-bet, and GzmB mRNA were also elevated." (PMID 38384806, 2024). "While certain cytokines, such as members of the IFN family, can directly induce apoptosis in tumor cells, some cytokines such as IL-6, TNFα, and TGFβ can enhance cell proliferation and resistance to induced cell death, ultimately fostering tumor growth and progression." (PMID 39204319, 2024). "However, when produced by M2 macrophages or in chronic inflammation, TNF-α can support tumor progression by fostering angiogenesis, immune suppression, and cancer cell survival." (PMID 39766056, 2024). "CD8+ T cells and NK cells are capable of directly identifying and eliminating tumors, while CD4+ T cells contribute indirectly by producing cytokines like interferon-gamma(IFN-γ) and tumor necrosis factor-alpha(TNF-a), thus participating in anti-tumor immune responses." (PMID 38914941, 2024). "It has been shown that NO can promote TNF to kill tumor cells that are insensitive to TNF." (PMID 39175095, 2024). "The results of this study suggest that MZLAE may have a preventive effect on tumour initiation by reducing dysplasia development, as well as decreasing ROS, superoxide production, and inflammation through the downregulation of TNF-α and IL-6 proteins." (PMID 39290583, 2024). "One of such effects might be the observed upregulation of TNFα in immunosuppressive, tumor-infiltrating macrophages, previously reported in the context of chronic e-cigarette exposure." (PMID 39221247, 2024).
tumor (continued). "However, in MDA-231 cells, ACSL1 plays a crucial role in regulating the excessive production of TNFα-mediated inflammatory processes related to tumor growth." (PMID 39524444, 2024). "Recent studies have shown that activation of the STING pathway can lead to a shift in TAM polarization from M2 to M1, enhancing the secretion of pro-inflammatory cytokines such as TNF-α and IL-12, which are crucial for T cell activation and anti-tumor immunity." (PMID 39712021, 2024). "TNF (tumor necrosis factor) is expressed by a variety of cells, including tumor cells." (PMID 39206193, 2024). "Likewise, solid tumor preclinical models administered an antibiotic cocktail of vancomycin, imipenem, and neomycin, showed impairment of CpG-oligonucleotide immunotherapy, which affected tumor growth, survival, TNF, and cytokine production." (PMID 39599889, 2024). "The underlying reasons for this correlation could be multifaceted, involving complex interactions between the RDW and various inflammatory markers, cytokines like IL-6 and tumor necrosis factor-alpha, which are known to influence the behavior of tumor cells." (PMID 38791033, 2024). "In BRCA patient tumor samples, the KDM7A-DT expression is linked to stress-induced pathways such as interferon response, TNFα signaling, aerobic and anaerobic metabolism, apoptosis, extracellular vesicle process, immune characteristics, and the EMT Type II phenotype." (PMID 38756663, 2024). "Transfer of TNF-conditioned WT but not TNFR1-deficient BMDCs resulted in half as many CD45+ tumor-infiltrating cells as medium-conditioned BMDCs." (PMID 39178856, 2024). "Early research demonstrated that exogenous TNF-α could promote the destruction of tumor vasculature, thereby indirectly leading to the necrosis of tumor cells." (PMID 38840908, 2024). "Furthermore, CXCR-4 up-regulation, through TNF-α, mediated tumor cell motility and the production of inflammatory cytokine and chemokine receptors/ligands, including CXCR4." (PMID 39609700, 2024). "Besides, M1 macrophages can facilitate tumor neoangiogenesis while suppressing anti-tumor immunity by up-regulating pro-inflammatory molecule expression (iNOS, TNF-α, and IL-1β), thus exhibiting anti-tumor activity." (PMID 37735297, 2024). "We found that mPGES-1/PGE2/EP4 signaling in tumor cells is protective against antitumor immunity through at least 2 mechanisms: (i) increased intrinsic resistance to the cytotoxic effects of TNF-α, and (ii) creation of an immunosuppressed environment through the production of adenosine." (PMID 39298269, 2024). "The adhesion of tumor spheroids to colon epithelium and myofibroblast monolayers modulated the proinflammatory cytokines IL‐1 beta, IL‐6, TNF‐alpha and radicals (ROS and NO) levels in a tumor grade‐dependent manner, with a significant increase of IL‐6 production in advanced CRC." (PMID 38962943, 2024). "On the other hand, TNFα, another cytokine, can have a dual role in the tumor microenvironment." (PMID 38890285, 2024). "Via restoring an imbalanced immune system, parasites and their antigens were able to stimulate the MyD88 pathway and release robust pro-inflammatory cytokines such as INF-γ, TNF-α, IL-1, IL-2, IL-12, and others, thus creating an immunostimulant environment that is hostile to tumor cells." (PMID 39367471, 2024). "Additionally, through the secretion of apoptotic molecules such as TNF-alpha, macrophages exert direct cytotoxic effects on cancer cells, highlighting their multifaceted role in tumor suppression." (PMID 38730626, 2024). "The enriched pathways in the hA-MSCs provided evidence for increased cell migration, which can be partially attributed to the intrinsic homing property and recruitment of hA-MSCs to the tumor site mediated by released inflammatory cytokines such as IL6 and TNF-α from tumor cells." (PMID 38333871, 2024).